IL2 (interleukin 2)
Diseases named in the same sentence as IL2 in open-access papers (continued):
Sharing a sentence is not in itself a finding about the gene and the disease.
capillary leak syndrome (continued). "Vorinostat combined with Retinoic Acid caused grade 3 hematologic toxicity at maximum in the six evaluated patients in a phase I trial, whereas systemic IL-2 and GM-CSF administration caused grade 3 to 4 capillary leak syndrome and hypotension in around 20% and 10% of patients." (PMID 27471639, 2016). "In an attempt to develop a more manageable and better tolerated therapeutic schedule it has been decided to try a short IL-2 infusion repeated every 21 days, to add corticosteroids to reduce the risk of capillary leak syndrome, and to add radiotherapy to exploit the abscopal effect." (PMID 25245327, 2014). "Despite its therapeutic efficacy, HD IL-2 is associated with numerous side-effects, in particular, capillary leak syndrome (CLS) from lymphoid infiltration, which has been observed histologically in many organs." (PMID 34777395, 2021). "However, NK-92 cells are highly dependent on the cytokine interleukin-2 (IL-2), which has toxicity and may cause capillary leak syndrome." (PMID 28785259, 2017). "Cytokine therapies, such as high-dose interleukin-2 (IL-2), stimulate the immune response but have severe toxicity, including capillary leak syndrome and multi-organ failure, which limits their use." (PMID 40142960, 2025). "Patients can be treated with interleukin 2 (IL-2) and IL-15 to induce the production of NK cells, but this can lead to life-threatening toxicity and capillary leak syndrome." (PMID 39351437, 2024). "Unfortunately, IL-2 immunotherapy is accompanied by substantial side effects such as acute episodes of capillary leak syndrome and reduction of neutrophil function, which are also triggered by the induction and high cytotoxicity of LAK cells." (PMID 38893211, 2024). "Nevertheless, high IL-2 doses pose challenges due to serious side effects such as capillary leak syndrome, which can complicate LAK cell therapy in clinical practice." (PMID 39727496, 2024). "Despite these promising findings, the use of LAK cells in clinical settings faces a significant hurdle: the high doses of IL-2 often lead to serious side effects such as capillary leak syndrome." (PMID 39727496, 2024). "In prior studies wherein IL2 was used intravenously, systemic side effects such as capillary leak syndrome, hypotension, pulmonary edema, and renal dysfunction have been reported." (PMID 37182189, 2023). "IL-2 has a great propensity to induce adverse effects which includes “cytokine storm”, capillary leak syndrome and breathing difficulties which limits the widespread use of Proleukin®/IL-2 therapy in clinics." (PMID 33193321, 2020). "Although the pathophysiology of the IL-2-induced capillary leak syndrome seems multifactorial, binding of IL-2 to CD25 expressed on vascular endothelial cells has been reported to promote it." (PMID 30808414, 2019). "IL2 toxicity is mediated through lymphoid infiltration, a well-described capillary leak syndrome and the local effects of secondary cytokines." (PMID 30342473, 2018). "The major disadvantage of IL-2 is its toxicity, including severe capillary leak syndrome that can accompany this treatment." (PMID 28824651, 2017). "Compared to IL-2, the use of IL-15 minimizes capillary leak syndromes and has less side effects overall, thus providing a strong rationale to use IL-15 instead of IL-2." (PMID 28620386, 2017). "Pulmonary edema is a manifestation of capillary leak syndrome and is the most serious side effect of high-dose of IL-2 therapy." (PMID 26772545, 2016). "Hypotension, as a result of capillary leak syndrome, was one of the most commonly reported side effects from IL-2 treatment among the studies." (PMID 26557408, 2015). "In fact, there is substantial variation in the toxicities experienced by patients receiving high-dose IL-2 which are thought to result primarily from capillary leak syndrome (CLS) and lymphoid infiltration, the latter observed histologically in many organs." (PMID 25245327, 2014).
capillary leak syndrome (continued). "However, life-threatening capillary leak syndrome, leading to pulmonary and cerebral edema, respiratory distress, and heart failure can develop following intravenous administration of high dose IL-2." (PMID 38545115, 2024). "Although CAR-T cell activity could be supplemented with inflammatory cytokines such as high dose IL-2, however, systemic IL-2 treatment induces severe capillary leak syndrome and eventually end-organ dysfunction." (PMID 37691932, 2023). "Although treatment of NK-stimulating doses of IL2 or transplantation of LAK showed some positive effects in patients with advanced cancers, IL2 treatment was unfortunately associated with side effects of capillary leak syndrome." (PMID 37190251, 2023). "However, systemic IL-2 delivery is also well known to be highly toxic, leading to a broad set of adverse effects including capillary leak syndrome, thereby greatly limiting its therapeutic use." (PMID 36520915, 2022). "IL-2-induced capillary leak syndrome presents high levels of both IL-5 and eosinophils." (PMID 33916211, 2021). "However, standard HD IL-2 administration usually requires hospitalization and a dedicated medical team to monitor for capillary leak syndrome and other treatment-related toxicities." (PMID 34777395, 2021). "High-dose IL-2 was approved by the FDA for the treatment of patients with metastatic melanoma and metastatic renal carcinoma but caused severe systemic toxicity, including capillary leak syndrome, hypotension, hypoxia, and oliguric renal failure." (PMID 32508818, 2020). "Liver and lung are typically affected by the IL-2-induced capillary leak syndrome." (PMID 30808414, 2019). "Besides the limited therapeutic efficacy, one major disadvantage, particularly of high-dose IL-2, is the induction of the capillary leak syndrome, a potentially life-threatening adverse effect." (PMID 30808414, 2019). "Therapeutic IL-2 not only induces immune cell stimulation but may also induce hypotension and capillary leak syndrome." (PMID 29967609, 2018). "However, high-dose IL-2 therapy also induces systemic inflammatory responses, including capillary leak syndrome, heart failure, and pulmonary edema, thereby hindering the broad application of high-dose IL-2 therapy in the treatment of advanced RCC." (PMID 26772545, 2016). "Capillary leak syndrome is a life-threatening toxicity resembling septic shock that may occur with intravenous high-dose IL-2." (PMID 26557408, 2015). "However, use of high-dose infusional IL-2 is greatly hampered by significant toxicity, including capillary leak syndrome; continued use in pediatric sarcoma as a single agent seems unlikely." (PMID 26301204, 2015). "Additionally, while toxicity related to IL-15 is less likely than with IL-2, some patients still develop toxicity such as weight loss, rash, and hypotension (though capillary leak syndrome has not been observed)." (PMID 38545115, 2024). "Patients treated with IL-2 at high doses developed grade 3 and 4 adverse events (AEs) such as neurotoxicity, heart failure, and severe capillary leak syndrome (CLS)." (PMID 35806311, 2022). "IL2 class-specific AEs following FAP-IL2v treatment included pyrexia (59%), abnormal liver function test (58%), IRR (46%), edema (16%), and capillary leak syndrome (2%)." (PMID 39895413, 2025). "The central concern regarding the safety and tolerability of high-dose IL-2 primarily stems from IL-2's binding to CD25 on vascular endothelial cells, thereby precipitating capillary leak syndrome." (PMID 39218928, 2024). "Worth mentioning also is capillary leak syndrome (CLS), which may also occur in the course of treatment with IL-2." (PMID 36077623, 2022). "IL-2 toxicity can manifest as multiple organ syndrome, most significantly involving the heart, lungs, kidneys, and central nervous system in capillary leak syndrome (CLS)." (PMID 28443099, 2017).
capillary leak syndrome (continued). "Only four of five patients in the safety cohort completed all fourteen planned IL-2 doses, and none in the combination cohort did so, with most discontinuations being triggered by capillary leak syndrome." (PMID 41598579, 2026). "Eosinophilia from IL2 therapy has been proposed as a mechanism of capillary leak syndrome in humans which was not noted in this study population; however, a similar mechanism of IL2 induced eosinophilia appears to exist in dogs." (PMID 34383787, 2021). "In contrast to IL-2, IL-15 did not mediate activation-induced cell death (AICD), did not consistently activate Tregs and caused less capillary leak syndrome." (PMID 32508818, 2020). "There was not a statistically significant difference for AR, capillary leak syndrome and hypotension between GM-CSF vs IL-2 courses." (PMID 29967609, 2018). "Typical HD IL2-related toxicities including constitutional symptoms and capillary leak syndrome were observed in both cohorts without excess cardiac, hepatic, pulmonary, renal or skin toxicities beyond that expected with this agent." (PMID 30053905, 2018). "Although not statistically significant, capillary leak syndrome and grades 3–4 hypotension occurred at higher rates during the IL-2 courses." (PMID 29967609, 2018). "However, the widespread use of HD IL-2 therapy has been limited due to its significant toxic side effects in responding and non-responding patients, including capillary leak syndrome (CLS)." (PMID 39114660, 2024). "Interestingly, the half-life of IL-2 is increased in IL-2C; as such, low-dose IL-2C has immune enhancing effects that are comparable to those of high-dose IL-2 therapy without accompanying serious side effects such as capillary leak syndrome." (PMID 26772545, 2016). "Furthermore, there were no cases of grade 3 and 4 capillary leak syndrome, hypersensitivity reactions, bronchospasm, or allergic reactions with single-agent dinutuximab beta, while in studies where it was co-administered with IL-2, the incidences were 13–15%, 2–21%, 8%, and 15%, respectively." (PMID 37813959, 2023). "However, unlike IL-2, IL-15 is not required for the maintenance of Tregs; it does not induce activation-induced cell death (AICD) of CD8+ effector T cells; is required for the differentiation of NK, effector CD8+ and memory phenotype CD8+ T cells; and does not cause capillary leak syndrome." (PMID 26301204, 2015).
pancreatic cancer (62 papers, 2004 to 2025). "Due to limited tissue sample size, we had to omit multiple experimental groups, such as ones containing unarmed virus or normal human IL-2 encoding virus in settings where clinical pancreatic cancer samples were used." (PMID 40465005, 2025). "Another study showed that anti-PD-L1 VHH fused with two cytokines IL2 and IFNγ overcame the delivery barrier caused by an immunosuppressive tumor microenvironment and dense stroma surrounding tumors in an orthotropic pancreatic tumor model." (PMID 37746282, 2023). "Some of the proteins, such as IL10, ID1 and IL2, had been implicated as possible biomarkers of pancreatic cancer before." (PMID 28060763, 2017). "Previously, we have demonstrated in a nude-mouse pancreatic cancer model that the recombinant H-1PVs encoding IL-2 or the chemokine MCP-3/CCL7 cause recruitment of activated NK and monocytes to the site of tumor, resulting in a strong antitumor response." (PMID 23902851, 2013). "Overall, the triple therapy (IL-2/14d) effectively enhanced T cell infiltration in pancreatic cancer compared to CAR T cells alone, presumably by reducing the immunosuppressive characteristics of the TME." (PMID 40361460, 2025). "Our previous work used oral cancer, pancreatic cancer, and glioblastoma to demonstrate that the supernatant of IL-2 and anti-CD16 antibody-treated NK cells, as well as IFN-γ and TNF-α, mediate the differentiation of cancer stem-like tumors." (PMID 39851518, 2025). "The efficacy of IL-2 in adoptive DC immunotherapy for pancreatic cancer was examined both in vitro and in a xenograft mouse model." (PMID 38554155, 2024). "The targeted immune cytokine L19-Interleukin-2 (L19-IL2) induces extensive necrosis and proliferation restriction in pancreatic cancer with the indispensable role of NK cells." (PMID 39309440, 2024). "Previous studies have indicated that preoperative IL-2 immunotherapy increased the 2-year survival rate in patients with pancreatic cancer." (PMID 38554155, 2024). "Foxp3 also confers a suppressive phenotype on Tregs in pancreatic cancer cells by repressing the transcriptional activation of several T cell-stimulated target genes, such as Interleukin-2 (IL-2)." (PMID 38919615, 2024). "Treatment with cytokines, including drugs such as interleukin-2 (IL-2) and interferon-alpha, is critical for treating pancreatic cancer." (PMID 39087024, 2024). "We performed cytotoxicity assays with healthy donor-derived IL-2-activated NK cells and pancreatic cancer organoids from four patients." (PMID 37520563, 2023). "We confirmed that the level of PD-L1 on AsPC-1 pancreatic cancer cells was upregulated when the cells were cocultured with PBMCs and IL-2." (PMID 36284271, 2022). "To better characterize how this autocrine synthetic IL-2 circuit improves CAR T cell control of syngeneic pancreatic tumor models, we profiled the tumors in more depth during treatment." (PMID 36520915, 2022). "Treatment with BsNb PX4 combined with IL-2 considerably enhanced the cytotoxicity of hPBMCs against pancreatic cancer cell lines compared with the effect of IL-2 alone." (PMID 36284271, 2022). "The cytotoxicity of human peripheral blood mononuclear cells (hPBMCs) against pancreatic cancer cells was enhanced by the molecule in combination with IL-2." (PMID 36284271, 2022). "An anti-PD-L1 nanobody fused to either interleukin-2 (IL-2) or interferon-γ (IFNγ) demonstrated in vivo efficacy in treatment-resistant pancreatic tumors." (PMID 32793488, 2020). "Pancreatic tumor-bearing mice receiving dCAR-T cells released higher levels of cytokines, including IL-2, IL-6, IFN-λ and TNF-α, and showed a marked reduction in tumor growth compared to controls receiving CAR-T cells alone." (PMID 30987642, 2019). "Administration of an Onc.Ad expressing TNFa and IL-2 (Onc.Ad-IL2/TNFa) in five consecutive doses has significant antitumor effect in an immune competent Syrian hamster model of pancreatic cancer." (PMID 30298067, 2018).
pancreatic cancer (continued). "TIL were expanded from primary (P) or metastatic lesions (ML) in medium containing IL-2, IL-15 and IL-21 from 2 patients with pancreatic cancer (PDAC), 1 patient with glioblastoma (GB), 1 patient with fibrosarcoma (FS) and 1 patient with uveal melanoma (UVM)." (PMID 30400835, 2018). "Freshly harvested tumor tissues (colorectal and pancreatic cancer) were procured for TIL expansion using IL-2, IL-15 and IL-21." (PMID 30400835, 2018). "In our study, IL-2 concentration was increased in patients with cholangiocellular carcinoma and pancreatic cancer." (PMID 29410961, 2017). "In a co culture of NK(IL-2) or NK(IL-2CD16) cells with L3.6 pancreatic cancer, cancer cells showed increased caspase-3 expression." (PMID 26052286, 2015). "MUC1-CTLs were induced by co-culture with YPK-1, a human pancreatic cancer cell line, and then with interleukin-2." (PMID 24947606, 2014). "In this report, transfection of CIK cells with IL-2 demonstrated a prominent augmentation of antitumor immunity in vitro against pancreatic carcinoma cell lines via secreting significant amounts of IL-2." (PMID 15329148, 2004). "As this study focused on enabling PD-1/PD-L1 inhibition in PDAC, we next assessed the effects of virotherapy and chemotherapy on PD-L1 expression on pancreatic cancer cells, Panc-1 cells were infected with unarmed virus, virus armed with normal human IL-2 (Ad5/3-E2F-d24-hIL2) and Ad5/3-E2F-d24-vIL2." (PMID 40465005, 2025). "In addition, this gut microbiome can influence the serum level of IFN-γ and IL-2 and the pancreatic tumor immune infiltrates by increasing in numbers of CD8+ T cells, as well as activated T cells (CD8+/IFNγ+ T cells)." (PMID 40641916, 2025). "Initially, we reviewed the clinical data of patients, conducted univariate analysis, and combined with literature research on prognostic factors of pancreatic cancer, finally including 11 biological indicators (IL-2, IL-4, IL-6, IL-17, IFN-γ, NLR, LDH, CEA, AFP, CA19-9, β2-MG)." (PMID 41384105, 2025). "Whether IL2 promotes infiltration and antigen-presenting in pancreatic cancer needs to be investigated." (PMID 38554155, 2024). "The enhanced immuno-oncolytic virus efficacy of TPV/∆66R/mIL-2 and TPV/∆66R/mCCL-2 may be attributable to CCL-2- and IL-2-mediated negative regulation of pancreatic tumor progression through stimulation of the innate immune response." (PMID 39200298, 2024). "Notably, the PANCEP-1 trial, evaluating peri- and postoperative treatment with histamine dihydrochloride (HDC) and low-dose IL-2 in patients with primary resectable pancreatic cancer, has recently been initiated." (PMID 37623021, 2023). "In addition, a multicenter phase II study supported the efficacy and safety of immunotherapy, including 13-cis-retinoic acid and interleukin 2 in locally advanced pancreatic cancer patients." (PMID 35956413, 2022). "The administration of the anti-PD-1 IL-2 variant eradicated pancreatic tumors in orthotopic models, while the co-administration of anti-PD-1 and an irrelevant IL-2 variant immunocytokine did not." (PMID 33803078, 2021). "They reported the response duration of this combination therapy for pancreatic cancer was over 18 months and during this period, intravenous IL-2 in compared to subcutaneous administration leads to more platelet decrease, less platelet/lymphocyte decrease, and less Treg cells increase." (PMID 34781899, 2021). "We retrospectively analyzed the outcome of 42 patients with unresectable or recurrent pancreatic cancer treated with MUC1-DCs (MUC1-mRNA transfected DCs) and MUC1-CTLs (lymphocytes stimulated by co-culture with a MUC1 expressing human pancreatic cancer cell line and IL-2)." (PMID 24947606, 2014).